LMO1 (LIM domain only 1)
Diseases named in the same sentence as LMO1 in open-access papers (continued):
Sharing a sentence is not in itself a finding about the gene and the disease.
neuroblastoma (continued). "Our results also revealed that a subset of the GATA/TATA neuroblastomas with lower LMO1 expression can develop in neuroblastomas with the adrenergic CRC, due, in part, to aberrant upregulation of LMO3, a closely related LMO family member." (PMID 37183825, 2023). "Other Lim-only protein family members generally don’t compensate for diminished lmo1 expression in zebrafish MYCN-driven neuroblastomas." (PMID 37183825, 2023). "We found significantly reduced penetrance of MYCN-driven neuroblastoma in transgenic zebrafish with the T/T allele at the rs2168101 locus, concurrent with decreased lmo1 expression by these tumors, supporting our previous studies in neuroblastoma cell lines." (PMID 37183825, 2023). "The role of LMO1 as an essential cofactor for the adrenergic subtype of neuroblastoma appears to have been highly conserved throughout the 400 million years of evolution that separate zebrafish and human populations." (PMID 37183825, 2023). "Oldridge and colleagues identified SNP within a super-enhancer element in the intronic region of LMO1 which led to the high expression of LMO1 and neuroblastoma pathogenesis." (PMID 37274289, 2023). "In fish, as in human neuroblastomas, this permissive SNP drives high levels of expression LMO1, which is an essential transcriptional cofactor of the adrenergic CRC." (PMID 37183825, 2023). "Analysis of fish with these 3 genotypes showed a significantly reduced penetrance of neuroblastoma at 17 weeks of age in lmo1–/– compared with lmo1+/+ zebrafish (22% versus 70% respectively; P < 0.01)." (PMID 37183825, 2023). "Both LMO1 expression levels and the risk of developing neuroblastoma in children are associated with a single nucleotide polymorphism, G/T, that affects a GATA motif in the first intron of LMO1." (PMID 37183825, 2023). "Some studies have shown that LMO1 plays an essential role in the tumorigenesis of several types of cancer, including leukemia, breast cancer, and neuroblastoma." (PMID 36251702, 2022). "Variants in LMO1 have been associated with BMI44 and neuroblastoma and T-cell leukemia, which is of interest since the strongest genetic predictor for RLS is a variant in MEIS1 that affects cancers such as leukemia and neuroblastoma." (PMID 33239738, 2020). "We next sought to identify the individual target genes directly regulated by LMO1 in neuroblastoma cells." (PMID 31819055, 2019). "To verify that ASCL1 is directly regulated by LMO1, we analyzed the genomic loci bound by LMO1 in neuroblastoma cells." (PMID 31819055, 2019). "Although LMO1 frequently co-occupies target loci with GATA3 in both neuroblastoma and T-ALL cells, there was little overlap among the regulated enhancers between these two cell types." (PMID 31819055, 2019). "ASCL1 and LMO1 directly regulate the expression of CRC genes, indicating that ASCL1 is a member and LMO1 is a coregulator of the ADRN neuroblastoma CRC." (PMID 31819055, 2019). "Here, we identify the transcriptional signature driven by LMO1 in combination with MYCN in neuroblastoma cells." (PMID 31819055, 2019). "Downregulation of ASCL1 protein expression was observed in multiple LMO1-positive neuroblastoma cell lines after LMO1 knockdown." (PMID 31819055, 2019). "We next analyzed the chromatin status at LMO1 target loci in neuroblastoma cells and found that LMO1-enriched regions were frequently associated with active histone marks (H3K27ac and H3K4me1) in Kelly cells." (PMID 31819055, 2019). "Genetic knockdown of LMO1 inhibits the growth of neuroblastoma cells, whereas overexpression of LMO1 enhances proliferation in cells with low LMO1 expression." (PMID 31819055, 2019). "In this study, we also compared genomic loci bound by LMO1 and gene expression profiles after LMO1 knockdown between neuroblastoma and T-ALL cells." (PMID 31819055, 2019). "SNPs in CASC15, LMO1, and LIN28B are enriched in high-risk neuroblastoma and are correlated with neuroblastoma tumor aggressiveness." (PMID 29678897, 2018).
neuroblastoma (continued). "LMO1 rs110419 A>G, rs4758051 G>A, rs10840002 A>G, and rs204938 A>G were identified in a GWAS with 2,251 neuroblastoma patients and 6,097 controls of European ancestry." (PMID 30406033, 2018). "Knockdown of GATA3 results in decreased LMO1 expression and suppression of neuroblastoma cell growth." (PMID 29445148, 2018). "LMO1 rs110419 A>G, rs4758051 G>A, rs10840002 A>G, and rs204938 A>G) were analyzed in 256 neuroblastoma cases and 531 controls accrued from South China." (PMID 30406033, 2018). "RNA sequencing (RNA-seq) and gene set enrichment analysis (GSEA) indicated that matrisome, extracellular matrix-associated proteins, integrins coding signature genes were enriched in the neuroblastoma cell lines expression high levels of LMO1." (PMID 30406033, 2018). "In a zebrafish model of neuroblastoma, increased LMO1 synergizes with MYCN to promote tumorigenesis of aggressive phenotype neuroblastoma." (PMID 30200332, 2018). "The reported SNPs at previously identified neuroblastoma susceptibility loci, including 2q35 (BARD1), 6p22.3 (CASC15), and 11p15.4 (LMO1) were also nominally associated with 11q deletion." (PMID 28924153, 2017). "Its paralogue, LMO1, is a neuroblastoma oncogene which is duplicated in 12.4% of tumours, and is associated with aggressive disease." (PMID 28187790, 2017). "Among the eight relatively good prognostic markers, the neuroblastoma oncogenic roles of the highly-expressed LMO1 and the deletion of ARID1A have been evaluated." (PMID 28984200, 2017). "Genes that were significant with at least two variables include: BTNL2 for alopecia areata, NOD2 for Crohn’s disease, PLA2R1 for membranous neuropathy, LMO1 for neuroblastoma, and TNPO3, UBE2L3, HLA-DRA, and HIC2 for systemic lupus erythematosus." (PMID 26170196, 2015). "Of note, this low-level expression was significantly below the levels seen in an LMO1-expressing neuroblastoma cell line, and would be consistent with our finding of bivalent promoter marks over the LMO1 promoter in several haematopoietic lineages." (PMID 23302769, 2013). "Finally, there has been considerable recent interest in the role of LMO1 in neurological malignancies including work to suggest that levels of LMO1 may have a role in increased susceptibility to and increased aggressiveness of neuroblastoma." (PMID 23302769, 2013). "In a study of associations between SNPs and neuroblastoma, it has been observed that the rs2168101 G > T disrupts a binding site for the members of the GATA TF family within a SEE involved in LMO1 gene expression, ultimately contributing to neuroblastoma progression." (PMID 38902506, 2024). "Our studies in the zebrafish model, therefore, support a causative role for the G-containing allele at rs2168101 in upregulating lmo1 expression levels in developing neuroblasts, which increases the rate of initiation of MYCN-driven neuroblastoma in this model." (PMID 37183825, 2023). "Our finding that the relatively infrequent tumors that arise in the TATA/TATA zebrafish exhibit the mesenchymal CRC signature is consistent with our previous studies showing that a high level of LMO1 expression is required for the adrenergic CRC to form in human neuroblastoma." (PMID 37183825, 2023). "The adrenergic cell identity of neuroblastoma requires LMO1 as a transcriptional cofactor." (PMID 37183825, 2023). "It is also possible that the decreased tumor initiation of neuroblastoma in lmo1–/– or TATA/TATA zebrafish in our MYCN-driven neuroblastoma model may reflect a role of lmo1 function in normal development of the PSNS." (PMID 37183825, 2023). "Similarly, analysis of 153 primary human neuroblastoma samples by RNA-Seq showed a weak inverse correlation between LMO1 expression and the expression levels of the other LMO family members (R ≥ –0.3, P < 0.05)." (PMID 37183825, 2023).
neuroblastoma (continued). "Higher levels of LMO3 expression occurred in some of the human neuroblastomas corresponding to cluster 2h based on the adrenergic score, explaining how the adrenergic signature can form in these tumors despite relatively low levels of LMO1 expression." (PMID 37183825, 2023). "Knockout of lmo1 in zebrafish reduces the penetrance of MYCN-induced neuroblastoma." (PMID 37183825, 2023). "Our hypothesis is that, by preventing high levels of lmo1 expression in neuroblastoma, the TATA/TATA genotype blocks the formation of the adrenergic CRC because this CRC requires high levels of the lmo1 cofactor." (PMID 37183825, 2023). "Silence of LMO1 may suppress the growth of neuroblastoma cells with high LMO1 expression, whereas overexpression of LMO1 in neuroblastoma cells with low LMO1 expression promotes proliferation." (PMID 35280742, 2022). "SNP rs2168101 resides in SE of the first intron of LIM domain only 1 (LMO1), and SNP rs539846 locates in the intron 3 of B cell lymphoma 2 (BCL2)-modifying factor (BMF) SE, both of them influence neuroblastoma and chronic lymphocytic leukemia (CLL) susceptibility, respectively." (PMID 32278350, 2020). "However, there was very little overlap in these LMO1-bound regions between Kelly neuroblastoma and Jurkat T-ALL cells, indicating that LMO1 and GATA3 bind different lineage-specific enhancers." (PMID 31819055, 2019). "LMO1 regulates genes in a tissue-specific manner and co-binds to the enhancers of genes regulated by the CRC transcription factors that underlie cell state in ADRN neuroblastoma." (PMID 31819055, 2019). "Accumulating evidence implicates LMO1 as a critical factor in the ADRN subtype of neuroblastoma." (PMID 31819055, 2019). "Similarly, genes and pathways regulated by LMO1 knockdown in neuroblastoma cells were distinct from those in T-ALL cells." (PMID 31819055, 2019). "Importantly, here we provide an insight into the mechanisms by which LMO1 contributes to the ADRN neuroblastoma pathogenesis." (PMID 31819055, 2019). "LMO1–4 are engaged in a broad spectrum of developmental processes, and found to be involved in the initiation or the progression of T cell leukemia, breast cancer as well as neuroblastoma, to date." (PMID 30406033, 2018). "Although numerous subsequent studies have demonstrated the association of this critical gene with neuroblastoma risk, none have investigated the associations between LMO1 single nucleotide polymorphisms (SNPs) and Wilms’ tumor risk." (PMID 28881592, 2017). "We recently reported that genetic predisposition to neuroblastoma is mediated by an inherited G-T polymorphism that controls a super-enhancer within the first intron of LMO1 in these cells, promoting us to compare regulation of the LMO1 oncogene in neuroblastoma with that in T-ALL." (PMID 28260788, 2017). "Previous GWASs have discovered several inherited common variants in some chromosomal regions that are significantly associated with the risk of neuroblastoma, such as LINC00340 (also known as FLJ22536 or CASC15) at 6p22, BARD1 at 2q35, and LIM domain only 1 (LMO1) at 11p15." (PMID 27009839, 2016). "We intersected NB-associated common SNPs from a recent neuroblastoma GWAS35 with the dynamically ATRA-regulated SEs in KCNR cells and observed overlap at the LMO1 locus on chromosome 11p15." (PMID 38653778, 2024). "Furthermore, the result suggested a upward trend in LMO1 expression with the increase in the degree of malignancy of the tumor, which is consistent to previous results according to which LMO1 expression was widely expressed in human cancers of the lung, gastric, prostate and neuroblastoma." (PMID 35280742, 2022). "Moreover, LMO1 was found to confer human neuroblastoma cells invasive and migratory attributes." (PMID 30406033, 2018). "Zebrafish models of neuroblastoma uncovered the impact of co-expressing the MYCN oncogene and LIM domain only 1 (LMO1), which drives aggressive tumor growth and metastasis resembling high-risk human neuroblastoma." (PMID 39940643, 2025).
neuroblastoma (continued). "Previous studies have shown that LMO1 is involved in T-cell Acute Lymphoblastic Leukemia (T-ALL) and neuroblastoma, and its role in BC, particularly in the TCGA Cluster 5, supports its potential as a marker for aggressive cancer phenotypes." (PMID 40076569, 2025). "There were 7 neuroblastomas with TATA/TATA genotypes, which showed significantly lower LMO1 expression levels than GATA/TATA or GATA/GATA tumors (P < 0.005)." (PMID 37183825, 2023). "Ninety transcription factor genes were expressed significantly lower in neuroblastomas from both TATA/TATA and lmo1–/– zebrafish than in tumors in the GATA/GATA background." (PMID 37183825, 2023). "Consistent with human neuroblastomas, lmo1 mRNA expression levels in neuroblastomas from GATA/GATA fish were significantly higher than in tumors from either TATA/TATA or lmo1–/– fish." (PMID 37183825, 2023). "This is the case for the neuroblastoma tumors in our UMAP analysis (cluster 2h), which are characterized by lower LMO1 but high LMO3 expression levels." (PMID 37183825, 2023). "In neuroblastoma, ASCL1 appears to be under direct regulation by the LMO1 and MYCN oncogenes, and its overexpression correlates with poorer survival of patients with tumors." (PMID 37958729, 2023). "In addition, LMO1 expression levels are also higher in human neuroblastoma cell lines of the adrenergic subtype and lower in the mesenchymal type, consistent with our recent study showing that LMO1 is an essential transcriptional cofactor of the adrenergic CRC." (PMID 37183825, 2023). "We therefore analyzed gene expression in MYCN-induced neuroblastomas in GATA/GATA, TATA/TATA and lmo1–/– genetic backgrounds by RNA-Seq." (PMID 37183825, 2023). "Here, we first time show that in neuroblastoma cells iron chelator VLX600 inhibits mitochondrial respiration, decreases expression levels of MYCN/LMO1 (LIM domain only 1), and induces an efficient cell death regardless of MYCN status." (PMID 35805002, 2022). "LIM domain only 1 (LMO1), which as a hsa_circ_0021087 host gene, has been reported as an oncogene in multiple tumors, such as lung cancer, neuroblastoma and gastric cancer." (PMID 32154178, 2020). "The growth of neuroblastoma cell lines was more strongly inhibited by LMO1 knockdown than that of T-ALL cells, indicating that neuroblastoma cells are highly dependent on LMO1 expression for cell growth and survival." (PMID 31819055, 2019). "Subsequent studies showed that LMO1 overexpression significantly accelerates the latency, penetrance, and metastatic potential of MYCN-induced neuroblastomas in a zebrafish transgenic model." (PMID 31819055, 2019). "It is intriguing that LMO1 participates as a cofactor in CRCs containing GATA3 in both T-ALL and neuroblastoma; however, the remainder of the CRC of T-ALL and neuroblastoma remain completely distinct." (PMID 31819055, 2019). "In fact, we observed that MYCN frequently co-occupies the enhancers of target genes with LMO1, including those of CRC members, which characterize the ADRN subtype neuroblastoma." (PMID 31819055, 2019). "We chose two representative neuroblastoma cell lines (Kelly and SH-SY5Y), both of which express high levels of LMO1 protein and harbor permissive SNP alleles." (PMID 31819055, 2019). "Regulatory elements controlling ASCL1 expression are bound by LMO1, MYCN and the transcription factors GATA3, HAND2, PHOX2B, TBX2 and ISL1—all members of the adrenergic (ADRN) neuroblastoma core regulatory circuitry (CRC)." (PMID 31819055, 2019). "This variant was found to be located in open chromatin regions identified in 29 ATAC‐seq and 5 H3K27ac ChIP‐seq experiments in various neuroblastoma cell lines, but also showed the highest enrichment of TF binding sites, including MYCN, LMO1, GATA3, HAND2, ISL1, PHOX2B, and TBX2." (PMID 40525640, 2025).
neuroblastoma (continued). "Furthermore, expression of several genes associated with glioblastoma (STAT3, PDGFRA, MET, and NF1) and neuroblastoma (GATA3, ISL1, LMO1, and LIN28B) progression was downregulated at the transcriptional level in differentiated cells." (PMID 39859209, 2025). "LMO1 and LMO3 both contribute to the development of neuroblastoma." (PMID 38937681, 2024). "They observed that overexpressing LMO1 alone do not develop neuroblastoma but its overexpression along with increased MYCN expression led to enhanced neuroblastoma initiation and disease penetrance." (PMID 37274289, 2023). "This is mainly proven by the guided ectopic expression of MYCN (alone or in combination of LMO1 or ALK) in specific cell lineages of zebrafish models or genetically engineered mouse models (GEMM) which results in the development of neuroblastoma." (PMID 37274289, 2023). "LMO1, a member of LMO family, is reported as a dominant oncogene in neuroblastoma cells." (PMID 35280742, 2022). "In neuroblastoma, GATA3 plays a central role in regulating LMO1 expression." (PMID 32128448, 2020). "In support of these findings, neuroblastoma cell lines displayed high level expression of ASCL1 together with LMO1 by western blot analysis; however, ASCL1 was not expressed by any T-ALL cell lines examined." (PMID 31819055, 2019). "We also compared H3K27ac signals at regions bound by LMO1 in Kelly cells across a panel of neuroblastoma cell lines without MYCN amplification that expressed different levels of LMO1." (PMID 31819055, 2019). "Besides ASCL1, we found that the receptor tyrosine kinase gene RET was positively regulated by LMO1 and MYCN in neuroblastoma cells." (PMID 31819055, 2019). "Consistently, FLAG-tagged LMO1 could interact with endogenous GATA3 and LDB1 proteins when overexpressed in Kelly neuroblastoma cells." (PMID 31819055, 2019). "Similar H3K27ac profiles were observed at the same loci in multiple ADRN subtype neuroblastoma cell lines with high level of LMO1 expression but not in the MES subtype neuroblastoma cell lines with low level of LMO1 expression or in the T-ALL Jurkat cell line." (PMID 31819055, 2019). "Members of the LMO family, including LMO1, LMO2, LMO3 and LMO4, have been indicated to play important roles in the tumorigenesis of several types of cancer, including leukemia, breast cancer, and neuroblastoma." (PMID 30038707, 2018). "LMO1 is implicated as an independent predictor of poor patient survival in the clinic and its co-expression with MYCN was associated with an earlier onset and increased penetrance of neuroblastoma, indicating that the inhibition of MYCN might lead to a concomitant decrease of LMO1." (PMID 35805002, 2022). "Interestingly, the identified fusion RNAs included transcripts from well-known oncogenes, previously shown to be important for neuroblastoma biology (i.e., MYCN and LIM domain only 1 LMO1), and they involved chromosomal regions commonly gained or lost in high-risk neuroblastoma." (PMID 35269953, 2022). "Among all the factors taking part in NB tumorigenesis, recent genomic and functional investigations highlighted BARD1, LMO1, and ASCL1 as important actors in neuroblastoma tumorigenesis as well." (PMID 34884690, 2021). "However, ASCL1 overexpression did not rescue the cell growth inhibition caused by LMO1 knockdown, indicating that the effects of the CRC in maintaining neuroblastoma cell growth and survival depend on high levels of expression of each member of the CRC and the LMO1 CRC coregulator acting in concert." (PMID 31819055, 2019). "However, the involvement of LMO1 in the neuroblastoma CRC has not been elucidated yet." (PMID 31819055, 2019). "Interestingly, the lmo1–/– tumors did not highly express the signature genes from either the adrenergic or mesenchymal cell states, but instead expressed an alternative set of transcription factors with no previously defined role in either of these 2 neuroblastoma CRCs." (PMID 37183825, 2023).